NLRP3 (NLR family pyrin domain containing 3)
Diseases named in the same sentence as NLRP3 in open-access papers (continued):
Sharing a sentence is not in itself a finding about the gene and the disease.
Muckle-Wells syndrome (continued). "Muckle-Wells syndrome (MWS) is a rare autoinflammatory disorder and part of the cryopyrin-associated periodic syndrome (CAPS), caused by mutations in the NLRP3 gene encoding cryopyrin, a key component of the inflammasome complex." (PMID 40546599, 2025). "Previous reports have linked mutations in NLRP3 to familial cold autoinflammatory syndrome 1 (CAIS1) and muckle-wells syndrome (MWS), both inherited in an autosomal dominant manner." (PMID 39911581, 2024). "Dominant mutations in NLRP3 may lead to a spectrum of inflammatory diseases including familial cold autoinflammatory syndrome (FCAS, OMIM # 120100), Muckle-Wells Syndrome (MWS, OMIM # 191900), and chronic infantile neurological cutaneous and articular syndrome (CINCA, OMIM # 607115)." (PMID 27965898, 2016). "Abnormal NLRP3 inflammasome activation and excessive IL-1β secretion is the major reason of CAPS, and has been demonstrated in three clinical subtypes: neonatal-onset multisystem inflammatory disease (NOMID), Muckle-Wells syndrome (MWS), and familial cold autoinflammatory syndrome (FCAS)." (PMID 36891515, 2023).
coronary artery disease (63 papers, 2013 to 2026). "Main inflammasome biomarkers that are associated with coronary artery disease progression include IL‐1β, Nucleotide-binding oligomerization domain-like receptor family pyrin domain containing 3 (NLRP3), and caspase‐1." (PMID 39039680, 2024). "Although NLRP3 inflammasome-interleukin (IL)-1β has been implicated in the pathophysiology of coronary artery disease, its roles in cerebral arteriothrombotic micro-circulation disease such as CSVD remains unexplored." (PMID 36676165, 2023). "A study showed that NLRP3 rs10754558 polymorphism is associated with the occurrence and severity of coronary artery disease and the increase in serum concentration of IL-1β." (PMID 35464402, 2022). "In patients with the NLRP3 rs10159239 (rs9239) A allele, the increased NLRP3 expression was associated with a significant increase in the severity of coronary artery disease." (PMID 34349888, 2021). "NLRP3 was overexpressed in patients with coronary atherosclerosis and this is proved to be correlated with the severity of coronary artery disease and the atherosclerotic risk factors." (PMID 27446957, 2016). "Despite the well-established role of inflammation, particularly chronic inflammation, few studies to date have evaluated the role of the NLRP3 inflammasome and the molecular mechanisms underlying radiation-induced coronary artery diseases, highlighting a significant gap in the scientific literature." (PMID 41272654, 2025). "In addition, a previous study focused on the deterioration of bone vascular function in ischemic heart disease and found that inhibition of NLRP3 partially prevented the loss of type H vasculature after MI in mice." (PMID 35273164, 2022). "Ethanol-induced inhibition of the NLRP3 inflammasome activation in macrophages may represent a biological pathway underlying the protective effect of moderate alcohol consumption on coronary heart disease." (PMID 24244322, 2013). "CANTOS and several colchicine studies (COLCOT, LoDoCo, LoDoCo2) have confirmed the inflammatory hypothesis of coronary disease and demonstrated that targeting residual inflammatory risk and possibly the NLRP3 pathway may serve as an important strategy in reducing major adverse cardiovascular events." (PMID 38551014, 2021). "LBP alleviates MIRI by inhibiting pyroptosis through activating the Nrf2/NLRP3 axis, thus representing a promising therapeutic candidate for ischemic heart disease with the potential to improve patient outcomes." (PMID 41977382, 2026). "Understanding the mechanisms of post-ischemic inflammation, particularly involving IL-1β and NLRP3, is crucial for developing effective therapies to mitigate tissue damage and improve prognosis in ischemic heart disease patients." (PMID 40149903, 2025). "miR-22-3p exerts protective effects in coronary artery disease by downregulating NLRP3 in injured endothelial cells and suppresses cell proliferation, migration, and invasion in OSCC by targeting NLRP3." (PMID 41560727, 2025). "In particular, research has consistently indicated a link between NLRP3 activity and elevated levels of IL-1β and IL-18, correlating with the severity of conditions such as coronary artery disease." (PMID 40564905, 2025). "This review presents a brief update on immunomodulatory strategies in the continuum of conditions constituting ischemic heart disease and emphasising on the seemingly unifying mechanism of NLRP3 activation as well as modulation across these conditions." (PMID 39969632, 2025). "In this review, we analyze the interrelation between ROS and NLRP3 in ischemic heart disease and the effects of some NLRP3 inhibitors as possible therapeutic agents in this disease condition." (PMID 37507935, 2023). "The expression of NLRP3 is increased in the aorta of patients with coronary artery disease, and its expression correlates with the severity of coronary artery disease." (PMID 37396588, 2023).
coronary artery disease (continued). "In the past 5 years, more attention has been paid to the mechanism of the inflammasome in coronary heart disease, and the NLRP3 inflammasome-driven IL-1 release has led to atherosclerotic progression and accelerated vascular inflammatory response." (PMID 36873405, 2023). "Clinical studies have also confirmed that NLRP3 overexpressed in the aorta of patients with coronary heart disease patients undergoing coronary artery bypass grafting, and NLRP3 expression was positively correlated with the severity of coronary heart disease." (PMID 35707475, 2022). "Mechanism of electroacupuncture targeting NLRP3 inflammasome in the treatment of ischemic heart disease." (PMID 36337711, 2022). "Expression of the NLRP3 inflammasome has been reported in human plaques correlating with the severity of coronary artery disease (CAD), and also in circulating monocytes of acute coronary syndrome (ACS) patients, compared to controls." (PMID 36613465, 2022). "Clinical trials like LoDoCo, CANTOS, and COLCOT showed that targeting inflammatory pathways related to the NLRP3 inflammasome in patients with established coronary artery disease can be beneficial in the prevention of future cardiovascular events." (PMID 32648087, 2021). "In coronary artery disease, statins especially atorvastatin, can reduce expression of the NLRP3 inflammasome as well as downstream factors IL-1β and IL-18." (PMID 31354731, 2019). "In the blood samples draw from patients with coronary artery disease, the peripheral blood mononuclear cells express higher levels of NLRP3 inflammasome and the inflammasome‐dependent IL‐1β and IL‐18 cytokines when compared with the control patients." (PMID 28470940, 2017). "Future research should focus on elucidating colchicine’s effects on inflammatory cells concerning NLRP3 inflammasome; assessing potential benefits and risks in managing ischemic heart disease and developing therapies targeting IL-1β and NLRP3 pathways or inhibiting inflammasome activity." (PMID 40149903, 2025). "Additionally, DMF890, another small molecule NLRP3 inflammasome inhibitor, is currently in a phase 2 trial for coronary heart disease." (PMID 39508038, 2024). "Interestingly, a recent in vitro study demonstrated that splenic monocytes play a critical role in the progression of the ischemia in coronary artery disease through the upregulation of the splenic NLRP3 inflammasome, particularly CD11b+ and LY6G− splenocytes." (PMID 39039680, 2024). "This suggests that NLRP3/IL1β may be important for effective anti-inflammatory therapy as well as further improving the prognosis of ischemic heart disease." (PMID 38281937, 2024). "Notably, all clinical trials that obtained significant cardiovascular benefits (CANTOS, COLCOT, and LoDoCo2) so far in terms of anti-inflammatory treatment for coronary heart disease target the NLRP3/IL1β inflammatory axis." (PMID 38281937, 2024). "Ethanol-induced inhibition of NLRP3 inflammasome activation in macrophages may represent a protective effect of moderate alcohol consumption against coronary artery disease." (PMID 37560062, 2023). "Thus, AMPK and its regulated NLRP3 inflammasome can be used as potential new therapeutic targets for clinical prevention and treatment of ischemic heart disease." (PMID 33232283, 2020). "Moreover, expression of the NLRP3 inflammasome and its downstream inflammatory cytokines such as IL-1 and IL-18 was elevated in patients with coronary artery diseases or MI." (PMID 29850631, 2018). "Therefore, targeting the NLRP3 inflammasome is a potential therapeutic targeting in terms of reduction and early prevention of the progression of the myocardial ischemic zone in patients with stable coronary artery disease." (PMID 39039680, 2024).
coronary artery disease (continued). "The NLRP3 (nucleotide-binding oligomerization domain, leucine-rich repeat, and pyrin domain containing 3) inflammasome, the most characterized supramolecular complex and a potent mediator of inflammatory signaling, has been reported to be a marker of increased ischemic heart disease vulnerability." (PMID 35575239, 2022). "The first of these trials is a phase I study involving selnoflast, an NLRP3 inhibitor, designed to be administered to patients with TET2-CH and concurrent coronary artery disease (ISRCTN10520571)." (PMID 39119355, 2024). "Lastly, the third trial involves DFV890 (an NLRP3 inhibitor) and MAS825 (an anti-IL-1β/IL-18 agent), targeting patients with CH and coronary heart disease (NCT06097663)." (PMID 39119355, 2024). "Compared with healthy adults, the expressions of the NLRP3 inflammasome, ASC, caspase-1, IL-1β, and IL-18 in the serum of patients with coronary heart disease were significantly increased." (PMID 35464402, 2022). "The NLRP3 inflammasome initiates innate immune responses by sensing various danger signals and plays a crucial role in the pathological progression of atherosclerotic vascular injury, ischemic heart disease, and non-ischemic heart disease that cause cardiac dysfunction." (PMID 36588561, 2022). "On the other hand, in studies on diabetes mellitus and coronary artery disease, which are frequent complications in OSA, NLRP3 levels were found to increase in correlation with disease severity." (PMID 34349888, 2021). "The role of NLRP3 in radiation-induced coronary artery diseases has not yet been elucidated, but several studies have highlighted how inflammatory mechanisms are key actors in the onset and progression of these pathological conditions." (PMID 41272654, 2025). "Currently, the involvement of NLRP3 in radiation-induced coronary artery disease has not yet been demonstrated, and the literature on this topic is quite limited." (PMID 41272654, 2025). "Although studies have been done to identify these genetic changes individually in each disease, none of the studies have explored NLRP3 and CARD8 polymorphisms in subjects with the periodontal disease having coronary heart disease." (PMID 34199122, 2021). "In this review, we present the current knowledge regarding the function of NLRP in vascular disease, ischemic heart disease, and nonischemic heart disease and discuss the potential therapeutic options targeting the NLRP3 inflammasome." (PMID 29850631, 2018). "As far as plaque vulnerability is concerned, NLRP3 inflammasome expression was shown to be higher in patients with an ACS, followed by patients with stable angina, compared to those without coronary artery disease, showing a link between plaque vulnerability and clinical outcomes." (PMID 37765019, 2023). "However, in our study, we found that PEDF inhibited hypoxia-induced NLRP3 inflammasome activation via PEDFR, not LR, in cardiomyocytes, which shows a new direction for the treatment of ischemic heart disease though inhibiting the innate immune response." (PMID 27973457, 2016).
diabetic retinopathy (62 papers, 2016 to 2026). "In models of diabetic retinopathy and across other age-associated morbidities, increased Cx43 hemichannel activity has been shown to contribute to sterile chronic inflammation via activation of the NLRP3 inflammasome." (PMID 38970061, 2024). "DNA hypomethylation of NLR family pyrin domain containing 3 (NLRP3) is associated with increased risk of diabetic retinopathy, and that of TNFα, TGFβ1 and MCP-1 is considered responsible for its increased expression in the serum of patients with proliferative diabetic retinopathy." (PMID 36672234, 2023). "Activation of the NOD-like receptor protein 3 (NLRP3) inflammasome pathway has been implicated in Diabetic retinopathy (DR) pathogenesis, but its impact on DR development and progression remains unclear." (PMID 35624430, 2022). "Prior work from our laboratory demonstrated a role for REDD1 in NF-κB-dependent NLRP3 inflammasome activity in the context of diabetic retinopathy." (PMID 39920111, 2025). "It has been found that the specific inhibitor MCC950 can alleviate diabetic retinopathy by inhibiting NLRP3 inflammasome, but its concentration-dependent efficacy on retinal pathology needs to be explored." (PMID 40987781, 2025). "It has been demonstrated that activation of Nrf2 signaling negatively regulates NLRP3 inflammasome activity in diabetic retinopathy and cerebral ischemia−reperfusion injury." (PMID 38720901, 2024). "Studies in diabetic retinopathy indicate that Cx43 hemichannels lie upstream of inflammasome activity, with aberrant ATP release activating the P2 × 7 receptor, NLRP3 assembly and resultant caspase 1-mediated cleavage of IL1ß and IL18." (PMID 38970061, 2024). "In diabetic retinopathy, the NLRP3 inhibitor verapamil can significantly inhibit TLR4-mediated NLRP3 activation, reduce IL-1β and TNF-α levels and improve RGC survival." (PMID 39736512, 2024). "It achieves this partly through its ability to modulate the expression of Nrf2 and attenuate the activation of the NLRP3 inflammasome, particularly in subjects with diabetic retinopathy." (PMID 39057711, 2024). "Diabetic retinopathy is considered to be a chronic low-grade inflammatory disorder, while the function of NLRP3 inflammasome and pyroptosis activation in the pathogenesis of DR is well established." (PMID 37180116, 2023). "Wang Y, Tao J, Yao Y. Prostaglandin E2 activates NLRP3 inflammasome in endothelial cells to promote diabetic retinopathy." (PMID 33566983, 2021). "Recent findings show that the prostaglandin E2 and its cognate EP2 receptor plays role in inducing the expression of not only IL1β but also the inflammasome NLR family pyrin domain containing 3 (NLRP3) signaling in diabetic retinopathy." (PMID 34319011, 2021). "Hyperglycemia can activate NLRP3 inflammasome, promote secretion of inflammatory cytokines, and trigger cascade of inflammatory response, finally inducing diabetic nephropathy, diabetic retinopathy, and so on." (PMID 34707607, 2021). "The chronic inflammatory state involved activation of the NLRP3-inflammasome pathway in retinal endothelial cells and macrophages early in high fat diet-induced diabetic retinopathy." (PMID 31979105, 2020). "In diabetic retinopathy, a study showed that inhibition of autophagy in retinal pigment epithelial cells induced IL-1β release via ROS mediated NLRP3 inflammasome activation under high glucose condition." (PMID 30692509, 2019). "More and more studies showed that NLRP3 inflammasome plays a pivotal part in diabetic cardiovascular complications and diabetic retinopathy." (PMID 31088900, 2019). "In order to verify whether MCC950 can block the NEK7/NLRP3 pathway in diabetic retinopathy by binding specifically with NLRP3 and thus achieve the therapeutic effect, we used immunofluorescence localization to analyze the NEK7 expression level in the retina." (PMID 40987781, 2025).
diabetic retinopathy (continued). "It has also been shown that the hypomethylated state of the promoters of NLRP3, TGFβ1, MCP-1, and TNFSF2 may increase the risk of developing diabetic retinopathy." (PMID 39883715, 2025). "Similarly, TIL has been shown to reduce inflammatory responses in diabetic retinopathy through the Nrf2/TXNIP/NLRP3 inflammasome pathway." (PMID 39388398, 2024). "Moreover, the blocking of NLRP3 led to reduced VEGF secretion in a preclinical rat model of diabetic retinopathy." (PMID 39519338, 2024). "miRNA miR-590-3p, which has been proved to play an active role in inflammation, could directly target NLRP1 and NOX4 and inhibit pyroptosis in diabetic retinopathy through the NOX4/ROS/TXNIP/NLRP3 pathway." (PMID 35957838, 2022). "However, administration of folic acid downregulated inflammatory molecules (IL-1β and NLRP3) and oxidative markers in a mouse model of diabetic retinopathy." (PMID 34206804, 2021). "Additionally, PGE2 activates NLRP3 inflammation in endothelial cells to promote diabetic retinopathy." (PMID 34084773, 2021). "Folic acid (vitamin B9) may reduce inflammation (IL-1β and NLRP3) in a mouse model of diabetic retinopathy." (PMID 34206804, 2021). "Therefore, we elucidated a novel mechanism of inhibition of P2X7R-mediated activation of the NLRP3 inflammasome by H3 relaxin in the pathogenesis of diabetic retinopathy." (PMID 33584279, 2020). "NLRP3 activation may alsocontribute to the programmed cell death in diabetic retinopathy." (PMID 40758602, 2025). "In addition, in the retina, glibenclamide anti-edematous effects could result from the inhibition of the NOD-like receptor pyrin domain containing 3 (NLRP3) inflammasome and related neuroinflammation, known to be involved in diabetic retinopathy mechanisms." (PMID 34371786, 2021). "(2022) scrutinized the in vivo and in vitro anti-inflammatory properties of 3TC in a murine model of diabetic retinopathy, probing the impact of targeting the P2X7/NLRP3 signaling cascade on apoptosis and pyroptosis." (PMID 39220368, 2024). "CCs can also induce inflammation via the NLR family pyrin domain-containing 3 (NLRP3) inflammasome that mediates formation of activated IL-1β, a key inflammatory mediator in diabetic retinopathy." (PMID 37311879, 2023). "Recently, another NRTIs, i.e., lamivudine, was shown to inhibit the P2X7R and prevent diabetic retinopathy, thus reinforcing the role of the P2X7R and NLRP3 in its pathogenesis." (PMID 34281162, 2021). "Accumulating evidence implies that inflammasome activation contributes to tissue damage in various ocular diseases, including glaucoma, diabetic retinopathy and AMD, and aberrant activation of the NLRP3 inflammasome was demonstrated in uveitis patients and murine models of uveitis." (PMID 36430674, 2022). "By inhibiting the activation of NLRP3, ASC, caspase-1, and NF-κB to reduce the production of IL-1β and IL-18, propelling RvD1 to be expected an effective means to alleviate the progression of diabetic retinopathy." (PMID 33967796, 2021). "Meanwhile, the inhibition of P2X7R significantly reduced the expression and activation of the NLRP3 inflammasome, indicating that the initiation of NLRP3 inflammasome activation is dependent on the activation of P2X7R mediated by AGE–BSA–induced diabetic retinopathy." (PMID 34925047, 2021). "For example,the optical imaging method OCT is a high-resolution, noninvasive opticalimaging method that is widely used to diagnose diabetic retinopathy,but this imaging method is not able to detect NLRP3 inflammasomesand distinguish inflammatory cells from normal cells." (PMID 40758602, 2025).